LAPTM4B (lysosomal protein transmembrane 4 beta)
Diseases named in the same sentence as LAPTM4B in open-access papers (continued):
Sharing a sentence is not in itself a finding about the gene and the disease.
cancer (continued). "Overexpression of LAPTM4B-35 promotes antiapoptosis, proliferation, migration, invasion and multidrug resistance of cancer cells, and it also elicits oncogenesis of NIH 3T3 cells from mouse fibroblast cell line and L02 cells from normal human liver cell line." (PMID 27542271, 2016). "Previous study demonstrated that LAPTM4B can motivate multidrug resistance of cancer cells by promoting drug efflux and anti-apoptosis by activating PI3K/AKT signaling." (PMID 25714029, 2015). "After integrating the results, we selected LAPTM4B for further validation due to its proliferation and metastasis properties in various types of cancers." (PMID 25714029, 2015). "Previous reports indicated that LAPTM4B-35 over-expression increased cell growth and proliferation, and promoted the progression of cancer cells towards highly invasive and metastatic stages." (PMID 25689860, 2015). "This analysis demonstrated that knockdown of LAPTM4B in serum starved cells molecularly mimicked effects of several anti-cancer agents including small molecular weight inhibitors of PI3K and MEK (LY294002 and U0126, respectively)." (PMID 26343532, 2015). "We performed microarray data analyses and revealed that LAPTM4B is significantly over-expressed in multidrug resistant cancer cell lines compared with drug sensitive cancer cell lines." (PMID 25714029, 2015). "Among the cases with GC, intestinal metaplasia was observed in the adjacent mucosa to cancer tissues in 20 cases, and 11 cases showed positive expression of LAPTM4B-35 in intestinal metaplasia glands." (PMID 25689860, 2015). "In the discovery cohort (157 cases with GC), 142 (142/157, 90.4%) cases showed positive expression of LAPTM4B-35 in cancer tissues." (PMID 25689860, 2015). "In previous studies, the same conclusions were got that LAPTM4B-35 was an independent prognostic factor in a wide range of carcinomas." (PMID 25689860, 2015). "Lysosomal-associated protein transmembrane-4 beta (LAPTM4B) is a potential proto-oncogene, whose overexpression is involved in cancer occurrence and progression." (PMID 23469012, 2013). "It has been reported that LAPTM4B was widely expressed in normal human tissues and obviously up-regulated in various types of carcinomas." (PMID 23469012, 2013). "The overexpression of LAPTM4B was proved to be a novel molecular maker of progression, invasiveness and poor prognosis in various cancers." (PMID 22984585, 2012). "While the membrane protrusions we observed were likely enhanced by LAPTM4b overexpression, such overexpression is common in numerous cancers and likely contributes to the metastatic potential of LAPTM4b -expressing cells." (PMID 22096579, 2011). "The Lysosome associated protein transmembrane (LAPTM) family is comprised of three members: LAPTM5, LAPTM4a and LAPTM4b, with the latter previously shown to be overexpressed in numerous cancers." (PMID 22096579, 2011). "Functionally, LAPTM4B promotes cancer cell proliferation 15 and metastasis." (PMID 41362742, 2026). "However, the exact molecular mechanisms by which LAPTM4B affects cancer progression remain a focus of future research." (PMID 40231269, 2025). "Techniques to visualize LAPTM4B expression in vivo could facilitate early cancer detection and monitoring of treatment responses." (PMID 40231269, 2025). "The study revealed that LAPTM4B is not only involved in chemoresistance by affecting drug efflux, but also promotes chemoresistance of cancer cells by activating the phosphatidylinositol 4,5-bisphosphate 3-kinase (PI3K)/AKT signaling pathway and regulating intracellular signaling networks." (PMID 40231269, 2025). "LAPTM4B stimulates cancer proliferation, autophagy and resistance to chemotherapeutic drugs." (PMID 39753521, 2025). "In addition, LAPTM4B promotes cancer cell migration by regulating epithelial mesenchymal transition (EMT), protein kinase B (AKT) phosphorylation, and matrix metalloprotein (MMP) release." (PMID 40231269, 2025).
cancer (continued). "LAPTM4B expression was different in different molecular or immune subtypes of cancer, which results in different survival in the overall population and particular subtype of cancer." (PMID 40092987, 2025). "Although multiple molecularly targeted agents have been developed, some targeted therapies might be ineffective; therefore, additional targets, such as LAPTM4B, are needed to treat cancer." (PMID 40231269, 2025). "The important role of LAPTM4B in cancer biology is increasingly recognized." (PMID 40231269, 2025). "Our results revealed the role LAPTM4B plays in pan-cancer and Ph+ B-ALL." (PMID 40092987, 2025). "Thus, it is evident that LAPTM4B plays a key role in tumors and offers possibilities for cancer therapy." (PMID 40231269, 2025). "The OS rates of 33 LAPTM4B-overexpressing cancers were evaluated." (PMID 38388484, 2024). "LAPTM4B is explored in ischemia-reperfusion injury, but studies mainly focus on its role in cancer." (PMID 38388484, 2024). "It has been shown that LAPTM4B takes a significant role in autophagy regulation in cancers." (PMID 39147759, 2024). "To evaluate how LAPTM4B expression affects cancer patient survival, we conducted survival analyses." (PMID 38388484, 2024). "Functional studies have shown that LAPTM4B promotes cancer growth and metastasis." (PMID 38902268, 2024). "LAPTM4B has been identified as an oncogenic protein that promotes malignance in various cancers." (PMID 38902268, 2024). "For each cancer cell line, we knocked out LAPTM4B via utilizing CRISPR-Cas9." (PMID 38902268, 2024). "Numerous studies have demonstrated an oncogenic role of LAPTM4B in various cancers." (PMID 38902268, 2024). "Furthermore, metabolomic profiling of cancer cells revealed that LAPTM4B knockout leads to a significant enrichment of ferroptosis and associated metabolic alterations." (PMID 38902268, 2024). "LAPTM4B expression significantly increased in HCC tissues compared with non-carcinoma tissues." (PMID 38388484, 2024). "Therefore, LAPTM4B expression significantly increased in HCC tissues compared to non-carcinoma tissues, which predicted poor prognosis." (PMID 38388484, 2024). "LAPTM4B has been reported to promote cancer cell growth by activating the AKT signaling pathway." (PMID 37176055, 2023). "LAPTM4B transforms normal human cells and promotes the proliferation and migration of cancer cells." (PMID 37759697, 2023). "LAPTM4B plays a cancer-promoting role in the progression of NPC and may be a potential target for NPC therapy." (PMID 32651973, 2021). "Overexpression of LAPTM4B results in poorer prognosis in various cancers." (PMID 32340207, 2020). "Staining for LAPTM4B-35 was always localized in the cytoplasmic compartment of cancer cells." (PMID 31827181, 2019). "Additionally, the new evidence stemming from this study contributes to the addition of our understanding of LAPTM4B in cancer development and progression." (PMID 30746305, 2019). "Collectively, our data propose that LAPTM4B may be a cancer biomarker for LAC and a potential therapeutic target which facilitates the development of a novel therapeutic strategy against LAC." (PMID 30940109, 2019). "LAPTM4B is up-regulated in many human cancer cells and has been suggested to be involved in recruitment of the leucine transporter to lysosomes, regulation of epidermal growth factor receptor lysosomal sorting and degradation, and facilitating Cer removal from late endosomes." (PMID 30481169, 2018). "LAPTM4B is a proto‐oncogene, which becomes up‐regulated in various cancers." (PMID 30255662, 2018). "LAPTM4B is a proto‐oncogene that is overexpressed in various types of cancers." (PMID 30255662, 2018). "LAPTM4B was obviously up-regulated in various types of cancers." (PMID 27391361, 2016). "It thus has been proposed that LAPTM4B is a cancer driver gene, and LAPTM4B-35 is an oncoprotein." (PMID 27542271, 2016).
cancer (continued). "In this work, we reported the design and synthesis of a far-red/near-infrared (FR/NIR) fluorescence light-up probe DBT-2EEGIHGHHIISVG, which could specifically visualize LAPTM4B proteins in cancer cells and tumour-bearing live mice." (PMID 26984064, 2016). "DBT-2EEGIHGHHIISVG is found to selectively light up LAPTM4B proteins in solution and cancer cells." (PMID 26984064, 2016). "It was therefore possible that LAPTM4B-35-knockdown by RNAi may provide a promising novel therapy strategy in LAPTM4B-35 over-expression GC or other cancers." (PMID 25689860, 2015). "All the data indicated that the intracellular miR-188-5p may modulate sensitivity of cancer cells to adriamycin through targeting LAPTM4B with important implications in the design of new therapeutic agents." (PMID 25714029, 2015). "It is also plausible to propose that this role for LAPTM4B may extend to other cell stressors such as chemotherapy and that targeting the lysosomal degradation pathway may help augment the anti-cancer effects of chemotherapeutic regimens." (PMID 26343532, 2015). "LAPTM4B-35 was over-expressed in most human malignant tumors and precancerous lesions." (PMID 25689860, 2015). "And LAPTM4B-35 may interact with some cancer-related proteins, like protein phosphatase 2A and protein kinase C." (PMID 25849595, 2015). "Moreover, the important role of LAPTM4B in cancer suggests the possibility to make it a potential target for anticancer therapies." (PMID 24651764, 2014). "Furthermore, the significant role of LAPTM4B in cancer suggests the possibility to make it a potential target for anticancer therapies." (PMID 24651764, 2014). "Moreover, LAPTM4b is overexpressed in various cancers and has been implicated in the tumorigenic process." (PMID 22096579, 2011). "Besides, we showed that LAPTM4B was related to different immune cells in various cancers." (PMID 40092987, 2025). "Moreover, LAPTM4B stimulates cancer cell stemness, autophagy, and drug resistance." (PMID 38902268, 2024). "However, it remains unclear whether LAPTM4B’s regulatory role on ferroptosis extends to other types of cancer." (PMID 38902268, 2024). "Carcinomas with LAPTM4B-35 over-expression may present more invasive characteristics." (PMID 25689860, 2015). "We further performed Cox proportional hazards regression analysis of LAPTM4B polymorphism with the tissue samples stratified by other common clinicopathological parameters including age, ER, PR, HER-2, lymph node status and the sizes of primary tumors at the time of cancer diagnosis." (PMID 22984585, 2012). "Collectively, these results establish that LAPTM4B promotes EGFR-TKI resistance by maintaining lysosomal acidification, thereby sustaining p-EGFR signaling and supporting cancer cell survival under TKI treatment." (PMID 41362742, 2026). "Therefore, LAPTM4B might be an immunotherapeutic factor in various cancers." (PMID 40092987, 2025). "Summary of Spearman’s correlation between LAPTM4B expression and drug response (IC50 value) in cancer cell lines based upon the GDSC dataset." (PMID 40092987, 2025). "LAPTM4B depletion leads to elevated MDA levels in all cell types, indicating that LAPTM4B suppresses ferroptosis in several different types of cancer cells." (PMID 38902268, 2024). "Due to the vital role played by lysosomes in cancer, a LRRS signature was constructed, including 8 genes, namely, CLN3, GBA, CTSA, BSG, APLN, SORT1, ANXA2, and LAPTM4B." (PMID 38114725, 2023). "Studies have shown that tumor cell proliferation is abrogated by inhibiting LAPTM4B-mediated activation of AKT signaling in addition to disruption of the interaction between LAPTM4B and SH3 domain-containing proteins to control cancer invasion and metastasis." (PMID 32651973, 2021). "LAPTM4B, RANKL OPG, YKL-40, and SIRT1 in serum showed a significant change in both cancer groups compared with control." (PMID 32102511, 2020).
cancer (continued). "Our results revealed a coamplification of the cancer and lipid transport related genes NDRG1 and LAPTM4B, as well as new genes potentially co-regulated and cooperating with LAPTM4B." (PMID 27711123, 2016). "Therefore, LAPTM4B silencing may improve the cancer cells' sensitivity to chemotherapeutic drugs." (PMID 25714029, 2015). "Inhibiting LAPTM4B activates AKT signaling and inhibits cancer cell proliferation." (PMID 40231269, 2025). "Additionally, we analyzed stromal and immune cell scores to investigate the relationship between LAPTM4B expression and the tumor immune microenvironment (TIME) across cancers." (PMID 40092987, 2025). "LAPTM4B, an oncoprotein that promotes active EGFR signaling in cancer cells and is required for the autophagy process induced by inactive EGFR, might represent a synergistic targeting molecule in cancer therapy." (PMID 40231269, 2025). "However, the expression of LAPTM4B was discovered lowly expressed in KIPAN, KIRC, KICH and PRAD, while the genetic alterations were mainly amplification in these cancers." (PMID 40092987, 2025). "KEGG analysis of the top 30 pathways indicated that LAPTM4B regulates ABC transporters, AMPK signaling pathway, Central carbon metabolism in cancer, and Cysteine and methionine metabolism, which are known to be central in cancer development." (PMID 38902268, 2024). "Together with our findings, LAPTM4B may interact with EGFR and play an important role in the pro-survival functions of EGFR in cancer cells." (PMID 30940109, 2019). "In HPV negative carcinomas, LAPTM4B-35 expression had no influence on OS (p = 0.8370 [Log Rank], p = 0.9806 [Gehan-Breslow]) or DFS (p = 0.6159 [Log Rank], p = 0.7349 [Gehan-Breslow])." (PMID 31827181, 2019). "Although LAPTM4B-35 seems to be a promising marker for a variety of carcinomas, there is currently no clinical data available on protein expression in HNSCC." (PMID 31827181, 2019). "Although previous studies have shown that AP4 could play a positive or negative role in chemotherapy sensitivity in different carcinomas, we have shown that AP4 depresses the chemotherapy sensitivity of HCC via LAPTM4B in this research." (PMID 29337428, 2018). "The overexpressed LAPTM4B-35 was an independent prognostic biomarker for NSCLC, which could predict cancer recurrence and poor over survival." (PMID 27486880, 2016). "LAPTM4B was not highly expressed in all tissues, its expression was high in the testis, heart, skeletal muscle and uterus, while we found that it was highly expressed in most cancers." (PMID 40092987, 2025). "The development of LAPTM4B inhibitors or modulators could provide new avenues for cancer treatment, especially for tumors that have not responded to conventional treatments." (PMID 40231269, 2025). "Similarly intense fluorescence signals are observed in pure DBT-stained HepG2 cells and L02 cells, revealing that pure DBT is not able to differentiate cancer cells (overexpressed LAPTM4B) and normal cells (low LAPTM4B expression) like DBT-2EEGIHGHHIISVG does." (PMID 26984064, 2016). "Recently, it was found that LAPTM4B can bind to EGFR, and subsequently enhance and prolong the EGFR signaling and initiate autophagy through a non-canonical EGFR signaling pathway and trafficking, which both facilitate the functions of EGFR on promoting cancer cell survival and proliferation." (PMID 27542271, 2016). "Whether the short (24 kDa) isoform of LAPTM4b, studied here, is also involved in promoting cancer is not known." (PMID 25998567, 2015). "LAPTM4B-positive cells were significantly accumulated in HCC tissues, but not in non-carcinoma tissues." (PMID 38388484, 2024). "Other factors such as LAPTM4B and PLD2 are overexpressed in a variety of cancers and promote cancer proliferation, invasion and metastasis; yet it is not known whether and how they exert cancer progression activities within the exosomal pathway." (PMID 36320056, 2022).
tumor (48 papers, 2007 to 2026). "LAPTM4B as a risk factor in a scoring system which has been shown to induce autophagy and promote tumour growth in HCC." (PMID 38461439, 2024). "By analyzing the TCGA-KIRC cohort using bioinformatics, we found M2 macrophages associated with tumor metastasis to be significantly increased in the immune microenvironment of patients with high expression of LAPTM4B." (PMID 36937841, 2023). "In in vitro studies, aberrant expression of LAPTM4B is closely associated with tumor cell growth, proliferation, migration, invasion, apoptosis resistance, autophagy initiation, as well as multidrug resistance." (PMID 32651973, 2021). "miR-132 is known as a tumor suppressor miR and some authors have associated it with reduced proliferation through its action on different targets (LAPTM4B, FOXA1)." (PMID 33505957, 2020). "In conclusion, this study examines for the first time the expression of LAPTM4B-35 in HNSCC tumour samples and in associated lymph node metastases at the protein level." (PMID 31827181, 2019). "The expression level of LAPTM4B in the serum of patients with LAC is significantly associated with the tumor progression and treatment effects, suggesting that detection of serum LAPTM4B will facilitate the diagnosis and better predict treatment response." (PMID 30940109, 2019). "Western blotting assays were examined to identify the underlying pathways involved in the tumor-promoting role of LAPTM4B." (PMID 30940109, 2019). "To explore the mechanism behind this tumour susceptibility, we first investigated the transcription factors that bind the region of the LAPTM4B promoter polymorphism." (PMID 29337428, 2018). "In our study, increased LAPTM4B expression was strongly associated with prognosis-related features, including tumor size, TNM stage and lymph node metastasis." (PMID 28476037, 2017). "This meta-analysis indicated that the LAPTM4B *2 allele was associated with increasing risk of multiple cancers, tumor initiation and development." (PMID 24746178, 2014). "Overall, our findings suggested that elevated LAPTM4B expression might be associated with a potential decrease in patients’ immune anti-tumor capabilities." (PMID 40092987, 2025). "LAPTM4B-35 expression was significantly associated with tumour stage." (PMID 31827181, 2019). "The data of TCGA (The Cancer Genome Atlas) database not only showed the same relationship between AP4 and LAPTM4B in mRNA level, but also suggested that LAPTM4B expression was associated with tumour grade and high‐expression LAPTM4B was a poor prognostic marker in HCC patients." (PMID 29337428, 2018). "However, the mechanisms that underlie the tumour susceptibility of patients with LAPTM4B allele*2 are still unclear." (PMID 29337428, 2018). "Overexpression of LAPTM4B-35 may be associated with tumor progression and poor prognosis in PCa and thus may serve as a new molecular marker to predict the prognosis of PCa patients." (PMID 24651764, 2014). "As the only difference between the two LAPTM4B alleles is the number of 19‐bp sequences in the 5′UTR, we hypothesized that some unique transcription factors that act in this polymorphism region may affect the biological function of LAPTM4B in tumour progression." (PMID 29337428, 2018). "In addition, the extra 53 amino acids at the protein N-terminus produced by LAPTM4B*2 could influence the biological activity and function of tumor cells and then induce oncogenic susceptibility." (PMID 24746178, 2014). "Analysis of clinical NSCLC tumor specimens confirmed elevated LAPTM4B protein expression in EGFR-mutant (exon 19 deletion) samples, relative to EGFR wild-type samples." (PMID 41362742, 2026). "Through analysis of clinical tumor samples, genetic manipulation, and functional assays, we identify the lysosomal protein LAPTM4B as a key driver of EGFR-TKI resistance by enhancing EGFR phosphorylation and downstream signaling." (PMID 41362742, 2026).